IL10 (interleukin 10)
Diseases named in the same sentence as IL10 in open-access papers (continued):
Sharing a sentence is not in itself a finding about the gene and the disease.
cancer (continued). "In parallel with considerable overproduction of other pro-inflammatory modulators, such as TNFα, IL-2, IL-6, MIG (CXCL9), MIP-1β (CCL4) and MIP-2 (CXCL2), we also detected a significantly lower secretion of IL-10 by tILC2s that contradicted the conventional ILC2 role in cancer." (PMID 38524132, 2024). "Furthermore, a decreased IL-1β and increased anti-inflammatory cytokine IL-10 levels were also detected after phagocytosis of cancer cells by VISTA+ M2 macrophages." (PMID 38553748, 2024). "In Cluster 3, research could focus on how stress and psychological factors affect salivary biomarkers in cancer survivors and the role of cytokines such as interleukin-6 and interleukin-10 in mental health." (PMID 39021745, 2024). "Importantly, Tregs constitute a key CD3+CD4+ subset that inhibits an effective anti-cancer immune response by producing the immunosuppressive cytokines IL-10 and TGF-β and consuming IL-2." (PMID 36980527, 2023). "Nitric oxide (NO), IL-6, IL-10, tumor growth factor-beta, indoleamine 2,3-dioxygenase, arginase-1, prostaglandin E2, vascular endothelial growth factor, and cyclooxygenase-2 are all examples of such factors that help cancers evade immunity." (PMID 37501757, 2023). "The overproduction of these two cytokines has been indicated in many other cancer types, indicating that increasing miR-155 expression by interfering with IL-6 and IL-10 could be an alternative approach for other type of cancer." (PMID 37928272, 2023). "Furthermore, our findings identified a concomitant increase in circulating levels of IL-10 in cancer patients post-operatively, which continued to increase 6 weeks post-surgery." (PMID 37359545, 2023). "The results showed that levels of IL-6, IL-8 and IL-10 in serum were higher in malignant tumor group than that in benign tumor and control group; the expression levels of IL-6 and IL-8 were significantly elevated in grade III than in grade I and II and was related to metastasis." (PMID 36693957, 2023). "Potential targets for cancer therapy include efferocytosis-related genes and pathways, such as phosphatidylserine, TYRO3, MerTK, indoleamine-2,3-dioxygenase 1, membrane-linked protein V, CD 47, TGF-β, and IL-10." (PMID 37853449, 2023). "Due to its conflicting immunologic effects, the role of IL-10 in cancer remains uncertain." (PMID 37501757, 2023). "A time course study with IL-10-neutralized MDSCs supernatant on Dox resistant cancer cells, showed downregulated p-STAT3 expression as early as 60 mins post treatment, whereas, IL-6- neutralized supernatant has showed decreased p-STAT1 activation after 240 mins of treatment." (PMID 38304256, 2023). "Moreover, several studies have found that increasing IL-10 expression levels correlate with poor outcomes in cancer patients." (PMID 36816967, 2023). "Moreover, we identified MDSC secreted IL-6/IL-10/IL-1β induced STAT1/STAT3/NF-κβ signaling axis as a targeted cascade to promote early drug resistance in cancer cells." (PMID 38304256, 2023). "While these differences might be explained by the dual function of IL-10, as an immunosuppressant (cancer-promoting) and as an antiangiogenic (cancer-inhibiting) agent, it also might be a result of differences in ethnicity." (PMID 37501757, 2023). "Single-chain fatty acids, such as butyrate, produced by the gut microbiota may inhibit cancer and inflammation by blocking activation of the NF-kB signalling pathway and by inducing differentiation of IL10-producing T cells and regulatory T cells." (PMID 38143746, 2023). "IL-10 act as an immunosuppressive cytokine in cancer immunity via diverse mechanisms 43-45." (PMID 37151396, 2023). "High level of IL-10 is also directly attributes to poor clinical outcome of cancer patients." (PMID 38304256, 2023). "IL-10, as a pivotal anti-inflammatory and immunoregulatory cytokine, also exhibits antinociceptive effects in various rodent models, such as neuropathic pain, osteoarthritis, and cancer pain." (PMID 37492521, 2023).
cancer (continued). "It has been described that under specific circumstances, IL-6 and IL-10 could favor cancer development." (PMID 37122717, 2023). "Furthermore, it has been found that NSCLC cells can acquire features similar to cancer stem cells (CSC) when exposed to TAM-derived interleukin-10 (IL-10)." (PMID 37641132, 2023). "More investment in investigation of IL-10 pathway therapy could be useful in cancer and other chronic diseases." (PMID 37359549, 2023). "Therefore, the aim of this meta-analysis was to clarify the correlations of the IL-10 rs1800896 and rs1800872 and IL-6 rs1800795 gene polymorphisms with the SCC risk, including subgroup analyses by ethnicity, control source, and cancer type." (PMID 37077342, 2023). "IL-10 has dual functions in regulating immunity and has been shown to amplify immunosuppressive functions in myeloid cells as well as to trigger potent antitumor immunity in patients with cancer." (PMID 36757800, 2023). "However, recent preclinical studies demonstrated a pegylated IL-10-induced regression of cancer via CD8 T cell activation." (PMID 37366887, 2023). "Therefore, IL-10 is to be avoided during the T-cell activation, as evidenced by the positive effects of blocking IL-10 during cancer vaccination." (PMID 36860873, 2023). "In addition, it’s well known that Th2 cells contribute to cancer progression and metastasis by secreting IL-4, IL-5, IL-10 and IL-13." (PMID 37950236, 2023). "Moreover, IL-10 circulating levels were found to be elevated in serum of various cancer patients, often accompanied by the increase of other inflammatory markers, and correlated with a poor prognosis." (PMID 37359549, 2023). "The current results indicate an increased expression of both interleukins in HepG2 cells, which are cancer cells that may already have altered IL-6 and IL-10 expression themselves." (PMID 37107193, 2023). "Furthermore, both Breg subsets, in particular the CD24hiIgDlo/−CD38hi Breg subset, of the cancer patients consisted of significantly more IL-10+ cells than the counterparts of healthy subjects." (PMID 37291146, 2023). "Furthermore, Fc-VFD inhibits the secretion of VEGF-A, IL-6, TGF-β, or IL-10 from endothelial, cancer cells, and M2 macrophage, which reprograms immunosuppressive TME." (PMID 35895109, 2023). "Among cytokine genes, IL-10 expression was higher in cancer samples than that in precancer samples." (PMID 37409975, 2023). "Although each of these cytokines is subject to a different regulatory mechanism, the orchestration of this response could be directed by IL-10, which plays an important role in the control of inflammation and cancer." (PMID 37629156, 2023). "IL-10 has multiple pleiotropic effects on immunoregulation and inflammation in cancers." (PMID 36831513, 2023). "IL-10 is a very important class of anti-inflammatory mediators that protects the host from overreacting to pathogens and microbiota, and it can play an irreplaceable role in sterile wound healing, autoimmunity, cancer and homeostasis." (PMID 36329841, 2022). "Probably, biopsy analysis for the virus receptor expression, PD1/PD1L expression, immune cell composition, as well as for such cytokines as TGFβ and IL-10 would help to establish efficient personalized cancer immunotherapy with available “off-the-shelf” virus vectors." (PMID 36140243, 2022). "Treatment with an FLT3 inhibitor, midostaurin, showed a significant decrease in the Treg population, reduction in the FOX3p mRNA expression in AML cells, and reduction in IL-10 levels, indicating a role for IL-10 as a potential biomarker for AML cancer treatment." (PMID 35159023, 2022). "Because they might affect IL-10 gene transcription and translation, resulting in abnormal cell proliferation and cancer development." (PMID 35186043, 2022). "IL6 directly affects cancer dynamics, while IL10 and IL12 do it by affecting cytotoxic cells." (PMID 35294447, 2022).
cancer (continued). "In addition, the concentration of LC3B+ extracellular vesicles appeared to markedly correlate with the increased expression of PD-L1 and IL-10 in monocytes from ascites or effusions of cancer patients." (PMID 36233088, 2022). "The biomarkers most significantly associated with short-term mortality were IL-6, IL-10, IL-8, MCP-1 (mainly inflammatory markers), FGF-21, ST1A1, 4E-BP1 and CST5 (classified by OLINK as cardiovascular markers) and FGF-23 (classified as a cancer marker)." (PMID 36209229, 2022). "Finally, we carried out qRT-PCR analysis and concluded that mRNA expression levels of CCL22 and IL10 were higher in HNSCC cancer tissues than in normal tissues." (PMID 35480305, 2022). "As regards the role of IL-10 in cancer, it was demonstrated that this cytokine might act as a double-edged sword." (PMID 35752792, 2022). "Hence these cells can support cancer growth through regulatory mechanisms such as interference with T cell trafficking, release of suppressive factors (IL-10 and TGF-β), and depletion of essential T cell amino acids." (PMID 36479100, 2022). "Furthermore, anti-inflammatory cytokine IL-10 can inhibit anti-cancer response by shifting CD4+ pattern to T regular pattern and promote Treg generation." (PMID 36417428, 2022). "We focused on this cytokine since IL-10 is frequently upregulated in various types of cancer." (PMID 35955576, 2022). "After Bonferroni correction adjusts P value, a nonsignificant association was found between IL-10 -592C/A polymorphism and cancer for the dominant model in Caucasians." (PMID 35919032, 2022). "Eight cytokines (IL-1β, IL-6, IL-10, TGF-β, CCL2, CXCL8, CSF-1, and VEGF) were identified to have higher expression values in the high-risk group than in the low-risk group, which was relevant to the progression, invasion, and metastasis of cancers." (PMID 36120553, 2022). "Several authors reported that IL-10 serum levels were important in cancer development." (PMID 36009467, 2022). "TAMs promote the malignant progression of cancer by producing cytokines such as IL‐10 in TME." (PMID 36372977, 2022). "Besides, small molecules such as vascular endothelial growth factor (VEGF), transforming growth factor-beta (TGF-β), and cytokines like interleukin-10 (IL-10) released by cancer cells or immunosuppressive cells are proved to be involved in this process." (PMID 35585567, 2022). "Inhibition of βGBP reduces the levels of IL-10 and IL-35 and impairs cancer cell growth." (PMID 36338731, 2022). "In addition, CD47 secreted significant levels of IL-10 via M2 macrophages differentiation to promote cancer cell migration." (PMID 35678681, 2022). "The functional association between FAT1 and TGF-β1/TGF-β2 cytokines and the association of FAT1 with IL-10 cytokine and PD-L1/L2 immune checkpoints have not been reported in cancers so far." (PMID 35720420, 2022). "IL-10 secretion directed by STAT3 in cancer cells also results in the arrest of antitumor immunity." (PMID 35401182, 2022). "In addition to the secretion of immunosuppressive biomolecules like interleukin-10 (IL-10) and transforming growth factor-β (TGFβ), cancer cells also release immunosuppressive extracellular vesicles (EVs), in particular, exosomes." (PMID 36510217, 2022). "The use of specific anti-IL-10 antibodies is a successful approach to show the relevance of IL-10 during hindlimb reperfusion after femoral artery ligation, chronic inflammation, certain types of cancer, and neuropathic pain." (PMID 36297479, 2022). "In an IL-10 knockout model of microbial-triggered colorectal carcinogenesis, the depletion of colonic macrophages by clodronate (a non-nitrogenous bisphosphonate) protected mice against inflammation and cancer." (PMID 35681791, 2022). "Moreover, IL-10 blockade can be considered a complementary treatment to improve the outcome of conventional or novel cancer therapies." (PMID 35752792, 2022).
cancer (continued). "Moreover, IL-10 production has been restricted to immune cells (e.g. monocytes and granulocytes), nonimmune cells (e.g. keratinocytes and epithelial cells), and cancer cells." (PMID 36437782, 2022). "In other words, although IL-10 is known as an anti-inflammatory or immunosuppressive cytokine, some studies revealed the immunostimulatory activity of this cytokine in several cancer types." (PMID 35752792, 2022). "SCFAs have been found to inhibit the activity of the enzyme histone deacetylase, which may increase the number of regulatory T cells and the production of interleukin-10 and transforming growth factor-β, promoting cancer cell apoptosis." (PMID 36570164, 2022). "For example, stress-induced Th1 suppression leads to a Th2-shift, an overproduction of IL-10 amongst others and may favor the development of different cancer types." (PMID 35422029, 2022). "The hypothesis that the presence of IL-10 during cancer would enhance the immune function of patients has been proposed." (PMID 36111230, 2022). "The IL10 is a key anti-inflammatory mediator ensuring protection of a host from over-exuberant responses to pathogens and microbiota, while playing important roles in immunotherapy for cancer." (PMID 35346107, 2022). "It was reported that IL-10 signaling blockade at the priming stage could induce stronger Ts cell responses, which is beneficial for treatment of chronic viruses and cancer." (PMID 33542929, 2021). "IL-10 is a potent anti-inflammatory cytokine, secreted by cancer and immune cells." (PMID 33466674, 2021). "IL-10 is produced by MDSCs, M2 macrophages and cancer cells." (PMID 34061898, 2021). "Interestingly, blocking IL-10 activity have been reported to promote active proliferation and expansion of T cells in cancer patients, thus facilitate the resolution of the immunosuppression observed in these patients." (PMID 34251989, 2021). "Therefore, it will be necessary to evaluate a potential therapeutic intervention by either inhibiting or promoting the IL10 pathway on a case-by-case basis in specific cancer types and patient subpopulations." (PMID 34583750, 2021). "And, that was a rationale for conducting an IL-10 cancer treatment phase 1 trial." (PMID 33912464, 2021). "They support the cancer cells by proceeding angiogenesis via adrenomedullin and secretion of vascular epithelial growth factors (VEGFs) while its immunosuppression function is mediated by expression of IL-10, PD-L1 (programmed death-ligand 1), and TGFβ." (PMID 34335844, 2021). "Moreover, FUCA2 level showed a positive relationship with most immunosuppression genes, including programmed death-ligand 1 (PD-L1), transforming growth factor beta 1 (TGFB1), and interleukin-10 (IL10) in most cancer types." (PMID 34745134, 2021). "In patients with cancer this increase in IL-10 could be detremental for patients undergoing surgery by contributing to postoperative NK cell suppression." (PMID 34768810, 2021). "Once IL-10 is secreted, it has complex effect on cancer growth." (PMID 34944793, 2021). "On the other hand, IL-10 negatively affects the clinical outcome of many cancer types." (PMID 34680190, 2021). "Once in the cancer stroma, CAFs can directly interact with monocytes and instruct them to adopt a pro-tumorigenic, immunosuppressive phenotype, partly by inducing their IL-10 secretion." (PMID 34944793, 2021). "Studies have shown that cancer cells can produce various factors, including IL (interleukin)-4, IL-10, granulocyte-macrophage colony-stimulating factor (GM-CSF), and tumor growth factor (TGF)-β, which can repolarize macrophages toward an anti-inflammatory (M2) phenotype." (PMID 34576042, 2021).
cancer (continued). "Cancer cells can also alter NK cell function by modulating the NK cell surface receptors, releasing soluble factors with immunosuppressive properties such as IL-10 and transforming growth factor beta (TGF-β)." (PMID 34867958, 2021). "The role of IL-10 in cancer has proven highly controversial with various contradictory findings." (PMID 34944729, 2021). "My original hypothesis is that IL-10 plus anti-GD2 antibody may activate the NK cell-mediated ADCC to kill cancer cells." (PMID 33912464, 2021). "Therefore, IL-10 also plays an important and paradoxical function in cancer immunotherapy via its potential to inhibit or activate IL-10 signaling." (PMID 33401586, 2021). "In our work, a general (non-cancer-specific) cohort, we found that another immunosuppressive tryptophan derivative, anthranilic acid, had a poor prognostic value, correlating with the maintenance of high interleukin-10 and -18 levels." (PMID 34517343, 2021). "Mouse models indicate IL-10 can actually augment cancer responses." (PMID 34489941, 2021). "Besides, IL-10 is harmful to cancer cells and evolution process cannot let cancer to express IL-10 receptor to harm itself." (PMID 33912464, 2021). "Indeed, exogenous IL-10 is being investigated as a therapeutic option in multiple cancer types, including CRC." (PMID 34489941, 2021). "It appears that the mechanism of immune suppression of atovaquone by MDSCs in our model may be through TGF-β and IL-10, which are potent immunosuppressive cytokines and induce Tregs that allow cancer cells to escape from immune surveillance." (PMID 34068008, 2021). "Therefore, further studies of IL-10-related cancer immunotherapy are still needed due to these complicated and contradictory biological effects." (PMID 34625124, 2021). "In line with our results, several studies have reported that increased IL-10 levels in the blood of patients with cancer may predict a worse outcome." (PMID 34944879, 2021). "In clinical cancer patients, IL-10 is upregulated to initiate an anti-cancer immune response." (PMID 33912464, 2021). "Though IL-10 is a well-studied cytokine, the role it plays in cancer therapy is still unelucidated." (PMID 34336101, 2021). "In contrast, evidence suggests that IL-10 can suppress cancer development and metastasis." (PMID 33578830, 2021). "Suppression by IL-10 of antitumor immunity mechanisms (preventing antigen presentation from transformed cancer cells to cytotoxic T cells) favors propagation of the cancer and reduces patient survival; IL-10 can therefore serve as a prognostic biomarker, especially at early stages of the disease." (PMID 34830096, 2021). "ILCregs may support cancer progression by means of IL-10 expression, which, in turn, may reduce gut inflammation." (PMID 34680190, 2021). "Additionally, a differential analysis demonstrated that hypoxia potentially influences extracellular matrix remodeling, glycolysis, and interleukin-10 signal activation in various cancer types." (PMID 34676217, 2021). "Another novel cancer immunotherapy being evaluated clinically involves the administration of IL10." (PMID 32802517, 2020). "IL-10 promoters tend to be hypomethylated in different cancer types." (PMID 32582189, 2020). "Either way, the strength of our work is validated by the fact that we could observe elevation in previously reported cancer-specific biomarkers in specific cancers, such as G-CSF, GM-CSF, IL-10, and PECAM-1 (seeTable 1 for HC to cancer differences)." (PMID 33108394, 2020). "Arg1 and iNOS were the markers of MDSC population activation, and the activated MDSCs could secrete IL6, IL8, and IL10 to enhance cancer progression." (PMID 32195173, 2020). "Given that C. jejuni induced pathologies include the activation of the mammalian target of rapamycin (mTOR) and were ameliorated by rapamycin treatment in IL-10−/− mice, it is noteworthy that urolithin-A was reported to downregulate mTOR dependent pathways in cancer cells." (PMID 33374868, 2020).